CHD5 (chromodomain helicase DNA binding protein 5)
Description:
ATP-dependent chromatin-remodeling factor that binds DNA through histones and regulates gene transcription. May specifically recognize and bind trimethylated 'Lys-27' (H3K27me3) and non-methylated 'Lys-4' of histone H3. Acts as a component of the histone deacetylase NuRD complex which participates in the remodeling of chromatin. Plays a role in the development of the nervous system by activating the expression of genes promoting neuron terminal differentiation. In parallel, it may also positively regulate the trimethylation of histone H3 at 'Lys-27' thereby specifically repressing genes that promote the differentiation into non-neuronal cell lineages. Regulates the expression of genes involved in cell proliferation and differentiation. In spermatogenesis, it probably regulates histone hyperacetylation and the replacement of histones by transition proteins in chromatin, a crucial step in the condensation of spermatid chromatin and the production of functional spermatozoa.
Synonyms: CHD-5; PMNDS
Tractability: PROTAC: ubiquitination databases record sites on it; its protein half-life has been measured.
Gene: Protein-coding gene on chromosome 1 (6,101,787 to 6,180,321, reverse strand). Ensembl gene ENSG00000116254.
Subcellular location: Nucleus; Chromosome
Subcellular location (Human Protein Atlas): Nuclear speckles; Nucleoplasm; Cytosol
Pathways (Reactome):
Chromatin organization: Interaction of NuRD complexes with transcription factors; NuRD complex assembly
Gene Ontology:
Molecular function: histone H3K27me3 reader activity; ATP hydrolysis activity; ATP-dependent chromatin remodeler activity; chromatin binding; DNA binding; histone binding; ATP binding; histone deacetylase binding
Biological process: chromatin remodeling; regulation of transcription by RNA polymerase II; cerebral cortex neuron differentiation; negative regulation of cell population proliferation; sperm DNA condensation; negative regulation of transcription by RNA polymerase II; regulation of cell differentiation
Cellular component: membrane; nuclear speck; nucleoplasm; nucleus; chromatin; chromosome; heterochromatin; NuRD complex
Genetic constraint (gnomAD): Loss-of-function variants: 68 observed, 217.07 expected, observed/expected ratio (o/e) 0.31, 90% interval 0.26 to 0.38. The upper end of that interval is the gene's LOEUF score, 0.38, which puts it in group 1 of 6, group 1 being the genes least tolerant of losing a copy. Missense variants: 1,798 observed, 2,592.8 expected, observed/expected ratio (o/e) 0.69, 90% interval 0.67 to 0.72. Synonymous variants: 1,055 observed, 1,060.8 expected, observed/expected ratio (o/e) 0.99, 90% interval 0.94 to 1.05.
Homologues: Orthologues: chimpanzee CHD5 (99% identical), macaque CHD5 (97% identical), pig CHD5 (97% identical), dog CHD5 (97% identical), rat Chd5 (95% identical), mouse Chd5 (95% identical), guinea pig CHD5 (94% identical), tropical clawed frog chd5 (83% identical), zebrafish chd5 (78% identical). Paralogues in human: CHD4 (70% identical), CHD3 (69% identical), CHD7 (23% identical), CHD9 (23% identical), CHD8 (22% identical), CHD6 (22% identical), CHD2 (21% identical), CHD1 (21% identical), SMARCA4 (18% identical), SMARCA2 (17% identical), EP400 (17% identical), SRCAP (16% identical), and 18 more.
Diseases named in the same sentence as CHD5 in open-access papers:
CHD5 is named in the same sentence as 70 diseases in open-access papers, as found by Europe PMC text mining. Sharing a sentence is not in itself a finding about the gene and the disease. The quoted sentences say what the papers report.
neuroblastoma (40 papers, 2009 to 2026). Neuroblastoma (NB) is the most common solid, extracranial childhood tumor. "In neurogenic tumors, such as high-risk neuroblastoma, CHD5 frequently exhibits heterozygous deletions." (PMID 41487470, 2026). "In various contexts, CHD5 is implicated as a potential tumor suppressor, in neuroblastomas, gliomas, and many common adult tumors." (PMID 39038036, 2024). "For example, CHD5 is located at 1p36.31 region and is associated with the lower overall survival of neuroblastoma." (PMID 37904225, 2023). "We then identified 32 characteristic genes for high-risk neuroblastoma based on random forest algorithm, among which CHD5 is a tumor suppressor at 1P36, which is often lost or silenced in poor prognostic neuroblastoma (NB) and many adult cancers." (PMID 35911385, 2022). "CHD5 expression is significantly lower in high-risk neuroblastoma tumors, but the role of mutations in modulating its function is poorly understood." (PMID 35768791, 2022). "In this large cohort of neuroblastoma patients, CHD5 and KIF1Bβ were the most frequently mutated 1p genes, and were associated with multiple other synchronous mutations." (PMID 35768791, 2022). "CHD5 was also discovered to be frequently lost or silenced in high-risk glioma and linked to poor prognosis in neuroblastoma (NB) and several adult cancers." (PMID 36361605, 2022). "Evidence that CHD5 functions as a tumour suppressor in human cancers has emerged principally from studies of neuroblastoma, wherein loss of the CHD5 locus on chromosome 1p36.3 is very common." (PMID 29907144, 2018). "Intriguingly, the loss of the similar functional gene CHD5 has been also linked to the progression of neuroblastoma tumors." (PMID 27009842, 2016). "Both CASZ1 and NuRD subunit CHD5 have been identified as chromosome 1p36 tumor suppressor genes in neuroblastoma, and both are frequently lost in high-risk neuroblastoma patients." (PMID 26296975, 2015). "Loss of CHD5 is correlated with a poor prognosis in neuroblastoma tumors, and neuroblastoma cells that express CHD5 are more responsive to treatment than those that do not express CHD5." (PMID 25247294, 2014). "1p deletion and epigenetic silencing of CHD5 have been suggested to account for the low expression observed in both neuroblastoma tumors and cell lines, as homozygous deletions or mutations were reported to be infrequent." (PMID 23226679, 2012). "In fact, other mechanisms have been suggested in other types of tumors, as CHD5 mutation or methylation is associated with KRAS or BRAF mutation in ovarian cancer, and CHD5 expression correlates with MYCN amplification in neuroblastoma." (PMID 22569290, 2012). "Loss of CHD5 was linked to the chromosomal deletion on 1p36 and promoter hypermethylation in neuroblastoma." (PMID 22645613, 2012). "By studying the association of mutational variants of candidate neuroblastoma genes with clinical, cytogenetic and pathological characteristics, and survival outcomes, we found 1p candidate genes CHD5 and KIF1Bβ to be most frequently mutated after ALK, ATRX, and BARD1." (PMID 35768791, 2022). "Likewise, few somatic CHD5 mutations have been reported in neuroblastoma patients, and only in the context of relapse." (PMID 35768791, 2022). "However, several of the previous studies have demonstrated that CHD5 was a tumor suppressor gene in neuroblastoma, and was associated with a poor prognosis." (PMID 35955624, 2022). "Previous studies revealed that truncation mutations of CHD5 occur in neuroblastomas." (PMID 29568352, 2018). "SCN7A and CHD5 have all been linked causally to neuroblastoma biology and prognosis." (PMID 25295525, 2014). "Indeed, in neuroblastoma loss of heterozygosity often occurs by promoter methylation of the remaining CHD5 gene." (PMID 24849318, 2014). "Loss of the chromatin remodeling ATPase CHD5 has been linked to the progression of neuroblastoma tumors, yet the underlying mechanisms behind the tumor suppressor role of CHD5 are unknown." (PMID 25247294, 2014).
neuroblastoma (continued). "In summary, we report that the differential expression of the neuron-specific protein CHD5 accurately defines NB risk groups and may represent a marker of outcome in neuroblastoma that can be tested by conventional immunohistochemistry." (PMID 20950435, 2010). "Interestingly, induction chemotherapy could restore the expression of CHD5 in tumor tissues of half of high-risk neuroblastoma patients and present good response to chemotherapy and radiotherapy." (PMID 33062682, 2020). "The chromodomain, helicase DNA-binding protein 5 (CHD5) is a potential tumor suppressor gene located on chromosome 1p36, a region recurrently deleted in high risk neuroblastoma (NB)." (PMID 20950435, 2010). "CHD5, a tumor suppressor at 1p36, is frequently lost or silenced in poor prognosis neuroblastoma (NB) and many adult cancers." (PMID 34789839, 2022). "This clinical case supports the role of CHD5 as a haploinsufficient tumor suppressor in neuroblastoma." (PMID 35768791, 2022). "The screening results of RF showed that EPS8L1, PLCD4, CHD5, NTRK1, and SLC22A4 were the feature differentially expressed genes (DEGs) of high-risk neuroblastoma." (PMID 35911385, 2022). "Survival analysis showed that CHD5 was generally associated with the prognosis of glioblastoma (GBM), low Grade Glioma (LGG) and neuroblastoma, where the low expression of CHD5 was associated with a worse prognosis in glioma patients." (PMID 35955624, 2022). "The screening results of the RF classifier showed that EPS8L1, PLCD4, CHD5, NTRK1, and SLC22A4 were the most characteristic DEG genes among high-risk neuroblastoma-related genes." (PMID 35911385, 2022). "We next focused on 1p-intact neuroblastomas and studied the mutational spectrum of neuroblastoma candidate genes (particularly chromosome 1 genes CASZ1, CHD5, PTPN14, KIF1Bβ, NTRK1, and TP73), and their association with clinical prognostic variables." (PMID 35768791, 2022). "In other studies, CHD5 was reported to be more preferentially expressed in tumors in the nervous system, especially in neuroblastoma with a deletion of the 1p36.3 region, and was shown to be a potential tumor suppressor gene in neuroblastoma." (PMID 35955624, 2022). "According to the position, expression pattern, and function of CHD5 in neuroblastoma cells and xenograft cells, CHD5 was identified as a tumor suppressor gene." (PMID 34616726, 2021). "Studies on neuroblastoma have found that high CHD5 expression is closely related to favorable clinical and biologic characteristics, while low expression or deletion is related to adverse characteristics such as MYCN amplification and poor prognosis." (PMID 33062682, 2020). "We found that the pull down of CASZ1a also pulled down CHD5, indicating that in neuroblastoma cells, these two chromosome 1p36 tumor suppressors interact with each other." (PMID 26296975, 2015). "Chromodomain-helicase DNA binding protein 5 (CHD5) is an important tumor suppressor gene deleted from 1p36.31 in neuroblastomas (NBs)." (PMID 26245651, 2015). "Previous studies demonstrated that CHD5 acted as tumor suppressor gene in a lot of cancers such as neuroblastoma, laryngeal squamous cell carcinoma, colon cancer, lung cancer and gastric cancer." (PMID 26287602, 2015). "Restoration of CHD5 expression inhibited proliferation and tumor growth in neuroblastoma, breast cancer and lung cancer cells." (PMID 24454811, 2014). "CHD5 expression has been shown to be epigenetically silenced by promoter hypermethylation in a variety of human cancers, including neuroblastomas, colorectal cancer, breast cancer, cervix cancer, hepatocarcinoma, gastric cancer and lung cancer." (PMID 24454811, 2014). "Several studies have suggested that CHD5 is a relevant tumour suppressor inactivated in neuroblastoma." (PMID 24849318, 2014).
neuroblastoma (continued). "In addition, CHD5 mutations have been implicated in head and neck squamous cell carcinoma, human prostate cancer, ovarian cancer, ovarian clear cell carcinoma, cutaneous melanoma, hepatocellular carcinoma, neuroblastomas, metastatic prostate tumors, breast cancer and colorectal cancers." (PMID 24454811, 2014). "Several cancer cell lines and tumors from neural (neuroblastoma and glioma) and epithelial (colon and breast) lineages have 1p36 deletions that encompass the CHD5 gene." (PMID 24454811, 2014). "The methylation status of the CHD5 promoter region from -841 to -246, which contains 58 CpG sites and is frequently methylated in neuroblastoma cell lines, was determined in 9 breast cancer cell lines, 30 primary tumors, and 10 normal breast tissues." (PMID 22569290, 2012). "Similar to miR-34a, CHD5 is also located at 1p36, and is frequently deleted and/or methylated in several human cancers including neuroblastoma." (PMID 23226679, 2012). "The promising therapeutic implications of restoring CHD5 expression in neuroblastoma has previously been shown by the reduced clonogenicity and xenograft tumor growth of neuroblastoma cell lines stably transfected with CHD5 cDNA." (PMID 23226679, 2012). "CHD5 expression has been suggested to serve as a biomarker for positive outcomes in neuroblastoma patients." (PMID 21931736, 2011). "In a recent study, chromodomain helicase DNA binding protein 5 (CHD5) was identified as a novel tumor suppressor gene (TSG) in neuroblastoma." (PMID 19840376, 2009). "In some cases of neuroblastoma, there are evidence that CHD5 expression is epigenetically suppressed by promoter hypermethylation, although this observation was not confirmed by another study." (PMID 19840376, 2009). "Subsequent research has further established CHD5 as a tumor suppressor in neuroblastoma." (PMID 41487470, 2026). "A previous study showed that the upregulation of PLCL1, mediated by the overexpression of CHD5, could suppress the invasion and migration of neuroblastoma cells." (PMID 38561388, 2024). "Furthermore, forced expression of CHD5 in neuroblastoma cells with 1p deletion suppresses the metastatic progress of neuroblastoma." (PMID 37904225, 2023). "Among neuroblastoma cell lines, in only 1 of 30 cell lines, was a V680L heterozygous missense mutation detected – a variant not affecting the H3-binding function of CHD5." (PMID 35768791, 2022). "Subsequent studies demonstrated that CHD5 is downregulated in neuroblastoma and is correlated with unfavorable clinical features and poor survival; restoration of CHD5 expression could inhibit clonogenicity and tumorigenicity." (PMID 33062682, 2020). "However, a large number of genes located within the 1p36 region have been proposed as tumor suppressors in neuroblastoma and other tumors, including CHD5, CAMTA1, miRNA-34a, CASZ1, KIF1B, and the HES gene family." (PMID 27014418, 2016). "Here we also evaluated whether CASZ1a interacts with another NuRD subunit CHD5, which is a neuroblastoma tumor suppressor gene." (PMID 26296975, 2015). "Previously, we had transfected CHD5 into several neuroblastoma lines (e.g., NLF, IMR5), and although there was dramatic inhibition of growth, clonigenicity and tumorigenicity, we did not see any substantial morphological change or neuronal differentiation in these lines." (PMID 26245651, 2015). "CHD5 resides within a region commonly deleted in neuroblastoma (1p36)." (PMID 24849318, 2014).
neuroblastoma (continued). "As a consequence, CHD5 mRNA and protein expression were up-regulated in neuroblastoma tumors and might contribute to inhibition of cell proliferation." (PMID 25322458, 2014). "CHD5 has also been identified as a candidate tumor suppressor gene in neuroblastoma." (PMID 22569290, 2012). "Furthermore, ectopic expression of CHD5 in neuroblastoma cell lines suppressed clonogenicity and tumor growth." (PMID 22569290, 2012). "CHD5 is frequently deleted in neuroblastoma and is a tumor suppressor gene." (PMID 21931736, 2011). "A role for CHD5 in cancer was first suggested by genetic mapping studies in neuroblastomas." (PMID 21931736, 2011). "CHD5 is present at a gene locus (1p36.31) deleted in about 35% of neuroblastoma." (PMID 19840376, 2009). "Finally, CHD5 can be silenced in neuroblastomas by MYCN-driven miRNAs." (PMID 34070411, 2021). "CHD5 and CTDSPL possess tumor suppressor activities in many cancers, including neuroblastomas, gliomas, and Non-Small Cell Lung Cancer (NSCLC)." (PMID 39038036, 2024). "CHD5 was a member of a 9 member family of CHD chromatin remodeling proteins, which was first identified in neuroblastomas on 1p36 in a region of most deletion." (PMID 26287602, 2015). "We also found that CHD5 represses transcription of WEE1, in both neuroblastoma and pancreatic cancer cell lines." (PMID 25247294, 2014). "Low levels of CHD5 expression have been found in neuroblastoma cell lines, as well as correlating with MYCN amplification and poor prognosis in neuroblastoma tumors." (PMID 23226679, 2012). "Although CHD5 has been shown to repress another PcG protein in neuroblastoma, BMI1 (a core component of PRC1), we did not observe an influence of CHD5 on BMI1 expression in HCC cells (data not shown)." (PMID 26517514, 2015). "It has been reported that the CHD5 promoter was strongly methylated in the –780 to –450 region in neuroblastoma cell lines with 1p36 deletions, but not cell lines with two copies of the CHD5 gene." (PMID 24454811, 2014). "Moreover, by whole exome sequencing, we demonstrated that NB exo-DNA represents the entire exome and that it carries tumor-specific genetic mutations, including those occurring on known oncogenes and tumor suppressor genes in neuroblastoma (ALK, CHD5, SHANK2, PHOX2B, TERT, FGFR1, and BRAF)." (PMID 33915956, 2021). "The expression of the Chromodomain-helicase DNA binding protein 5 (CHD5) gene was recently shown to be elevated after 7 days of CRA treatment in SH-SY5Y, NGP, and SK-N-DZ neuroblastoma cells, although the increased expression was seen after the induction of morphologic neuroblastoma differentiation." (PMID 27014418, 2016).